TIMP1 (TIMP metallopeptidase inhibitor 1)
Diseases named in the same sentence as TIMP1 in open-access papers (continued):
Sharing a sentence is not in itself a finding about the gene and the disease.
glioblastoma (37 papers, 2009 to 2026). The most malignant astrocytic tumor (WHO grade IV). "For example, it is said that CB1 activation increases the levels of Tissue Inhibitor of MetalloProteinase 1 (TIMP1) in certain cancers to cause mortalities, whilst in glioblastoma multiforme, it actually was downregulated to produce the same effect." (PMID 33809034, 2021). "In a previous study we found an association between a low TIMP-1 tumor immunoreactivity and increased survival for glioblastoma patients, when compared to moderate and high TIMP-1 tumor immunoreactivity." (PMID 27619981, 2016). "Interestingly, in patients with glioblastoma, it has been demonstrated that low tumor TIMP-1 immunohistochemical expression is associated with significantly longer survival, compared to high TIMP-1 expression." (PMID 35853933, 2022). "Tumor-derived exosomes can transport pro-angiogenic cytokines within glioblastoma, including VEGF, FGF, TIMP-1/2, IL-8, and IL-6, thereby instigating both angiogenesis and glioblastoma cell proliferation." (PMID 40821116, 2025). "In the case of the LN18 glioblastoma line, fraction #3 at lower concentrations slightly increased the TIMP-1 level in the culture medium after 24 h, 48 h, and 72 h of incubation." (PMID 40141020, 2025). "Caffeine decreases the invasion of glioblastoma cells In addition, it increases the mRNA and protein expression of tissue inhibitors of metalloproteinase-1 (TIMP-1), whereas MMP-2 is down-regulated." (PMID 39055867, 2024). "Either Sp1 or TIMP1 was highly expressed in glioblastoma patients and correlated with poor prognosis." (PMID 35778451, 2022). "A study showed that downregulation of uPA/uPAR inhibits angiogenesis in glioblastoma and endothelial cells by regulating tissue inhibitors of metalloproteinase-1 (TIMP-1) secretion, subsequently enhancing secretion of sVEGFR1, a known scavenger of VEGF." (PMID 35222418, 2022). "By constructing TIMP1 knockdown glioblastoma cell line, we further analyzed the role of TIMP1 in glioblastoma and found that TIMP1 promoted cell proliferation." (PMID 35685428, 2022). "In order to identify potential biomarkers of glioblastoma, knocking down TIMP1 in U-87 MG and U-118 MG cell lines can inhibit cell proliferation, migration, and invasion, suggesting that TIMP1 plays a carcinogenic role in glioblastoma." (PMID 35685428, 2022). "Crocker and colleagues’ data suggest that, in glioblastoma patients, a higher serum TIMP1 level at tumor presentation predicted shorter survival and that TIMP1 levels in the glioblastoma patients are significantly higher than in normal controls." (PMID 31861636, 2019). "Altogether, these results suggest that TIMP-1 is a stronger prognosticator in glioblastoma patients compared to CD63 and TIMP-4." (PMID 29523123, 2018). "The present study suggests that CD63 is highly expressed in glioblastomas and that TIMP-1 and CD63 interact." (PMID 29523123, 2018). "In contrast to the considerable variation observed in the TIMP-1 expression in glioblastomas, the variation in the CD63 expression was minor, and virtually all tumor cells were positive." (PMID 29523123, 2018). "We have previously identified tissue inhibitor of metalloproteinases-1 (TIMP-1) as a prognostic marker in glioblastomas." (PMID 29523123, 2018). "In our previous study, the immunohistochemical expression of TIMP-1 in both tumor cells and blood vessels was investigated in 72 glioblastoma biopsies." (PMID 27619981, 2016). "In contrast to the rather constant FISH ratio, we detected a broader variation in the TIMP-1 immunoreactivities in the glioblastomas." (PMID 27619981, 2016). "The authors found increased serum levels of TIMP-1 when comparing 36 glioblastoma samples to five control patients, hospitalized for elective spinal surgery, with no consideration of age and gender." (PMID 27619981, 2016). "In the present study we performed TIMP-1 FISH analysis on 33 glioblastomas (cohort II) to elucidate the frequency of TIMP-1 gene aberrations." (PMID 27619981, 2016).
glioblastoma (continued). "Based on these results, elevated TIMP-1 immunoreactivity in glioblastomas should be explained by other mechanisms than gene amplification." (PMID 27619981, 2016). "We detected a median plasma TIMP-1 level of 80.1 ng/ml (range 59.5–131.9 ng/ml) in the glioblastoma patients." (PMID 27619981, 2016). "The study thus suggests that TIMP-1 immunohistochemistry is the method of choice when studying TIMP-1 as a biomarker in glioblastomas." (PMID 27619981, 2016). "In the present study, we compared each glioblastoma sample to two healthy subjects matched by gender and age, since studies have suggested especially age and gender to significantly affect plasma TIMP-1 levels." (PMID 27619981, 2016). "The study suggests that TIMP-1 immunohistochemistry is the method of choice for future clinical studies evaluating TIMP-1 as a biomarker in glioblastomas." (PMID 27619981, 2016). "For the glioblastomas, the median plasma TIMP-1 was 80.1 ng/ml (range 59.5–131.9 ng/ml) and 76.4 ng/ml (range 70.0–84.3 ng/ml) for the matched healthy subjects." (PMID 27619981, 2016). "Significantly increased TIMP1 levels were also detected in patients with astrocytomas and glioblastomas compared to patients with meningiomas (p < 0.001 and p = 0.024, respectively), and in patients with glioblastomas compared to those with astrocytomas (p < 0.001)." (PMID 38474106, 2024). "We have also shown that expression of CD63 and TIMP‐1 appears to be correlated with glioblastoma." (PMID 37081824, 2023). "Likewise, BGB324 in combination with an EGFR inhibitor has been shown to increase the mRNA expression of TIMP1 in glioblastoma cells." (PMID 31917795, 2020). "Also, CD63 expression did not affect the prognostic potential of TIMP-1 suggesting that TIMP-1 is a more valuable prognostic marker in glioblastomas compared to CD63 alone or in combination with CD63." (PMID 29523123, 2018). "In addition, co-expression of CD63 and TIMP1 have also been shown in patients with glioblastoma and astrocytoma by the other group." (PMID 30222750, 2018). "The role of TIMP-1 as a biomarker has in recent years become increasingly interesting in relation to the second line treatment of glioblastomas consisting of the vascular endothelial growth factor antibody bevazicumab, administered in combination with the chemotherapeutic drug irinotecan." (PMID 27619981, 2016). "In addition, blood samples and biopsies were collected from 43 brain tumor patients, comprising 20 glioblastoma patients, and the TIMP-1 plasma levels were correlated to TIMP-1 immunoreactivity in the matched biopsies." (PMID 27619981, 2016). "Moreover we found that glioblastoma patients with a low TIMP-1 expression had a significant longer overall survival than patients with a moderate or high TIMP-1 protein expression." (PMID 27619981, 2016). "Furthermore, we measured TIMP-1 plasma levels in 43 brain tumor patients including 20 glioblastoma patients (cohort I)." (PMID 27619981, 2016). "In conclusion, high immunohistochemical TIMP-1 protein levels in glioblastomas were not caused by TIMP-1 gene amplification and TIMP-1 in plasma was low and not directly related to tumor TIMP-1 immunoreactivity." (PMID 27619981, 2016). "However, vice versa, EGFR was also shown to modify the HA induced expression of a number of genes associated with cellular invasion and proliferation i.e. plasminogen activator inhibitor-1 (PAI-1) or tissue inhibitor of metalloproteinases (TIMP-1) in glioblastoma cell lines." (PMID 21429221, 2011). "In terms of downregulated genes in glioblastoma, we found NDRG4, SERPINA3, RPN2, VIM, and TIMP1 to be differentially the most downregulated genes." (PMID 38769480, 2024). "Even when correlating glioblastomas versus astrocytomas, we showed a significantly increased level of MMP1, MMP3, MMP13, and TIMP1." (PMID 38474106, 2024).
glioblastoma (continued). "We found that TIMP1, ITGA5, FCGR2B, UPP1, ISG20, TSPAN4, and LOXL1 are potential biomarkers correlated with the immune infiltration events in patients with glioblastoma." (PMID 35778451, 2022). "Analysis of exosomes from glioblastoma cells showed that they are enriched with the proangiogenic factors VEGF, angiogenin, TGFβ, IL-8, IL-6, MMP2, MMP9, TIMP-1, TIMP-2, and CXCR4." (PMID 35740619, 2022). "Through analyzing patients’ clinical information and genetic profiles from online databases, TIMP1, ITGA5, FCGR2B, UPP1, ISG20, TSPAN4, and LOXL1 were identified as potential prognostic biomarkers for glioblastoma." (PMID 35778451, 2022). "Using double-immunofluorescence, we showed that TIMP-1 and CD63 were co-expressed in some glioblastoma cells." (PMID 29523123, 2018). "The proximity ligation assay showed TIMP-1 and CD63 proteins in close molecular proximity revealing these interacting molecules as red spots in the tumor cells of the glioblastoma biopsies." (PMID 29523123, 2018). "In conclusion, we found an increased expression of CD63 in glioblastomas as well as a weak correlation between CD63 and TIMP-1." (PMID 29523123, 2018). "In summary, these assays suggest that TIMP-1 and CD63 are located closely together and interact in glioblastomas." (PMID 29523123, 2018). "The present study suggests that scoring of TIMP-1 immunoreactivity is a better choice than measuring of TIMP-1 plasma levels or using TIMP-1/CEN-X ratios, in future studies evaluating TIMP-1 as a biomarker in glioblastomas." (PMID 27619981, 2016). "In order to investigate the TIMP-1 gene copy number, we produced a new TIMP-1 probe suitable for fluorescence in situ hybridization (FISH) and estimated the TIMP-1/Centromere region on chromosome X (CEN-X) ratio in 33 glioblastoma biopsies." (PMID 27619981, 2016). "In glioblastomas with a TIMP-1/CEN-X ratio of approximately 1, biopsies with a low TIMP-1 expression as well as biopsies with a high TIMP-1 expression were observed." (PMID 27619981, 2016). "Furthermore, in glioblastoma, the co-expression of TIMP-1 and stem cell markers, as well as the expression of CD63, has suggested a role for TIMP-1 and CD63 in cancer cell stemness." (PMID 37443843, 2023). "In addition, we used the SurvExpress analysis to further assess the prognostic value of TIMP1, ITGA5, FCGR2B, UPP1, ISG20, TSPAN4, and LOXL1 using other glioblastoma patient cohorts, including TCGA Glioblastoma and GSE4412." (PMID 35778451, 2022). "Consistently, analysis of the expression level of TIMP1 showed that it is correlated with negative patient survival and immune infiltration in glioblastoma and other cancer types." (PMID 35778451, 2022). "In exosomes derived from glioblastoma cells, seven proangiogenic proteins were found: angiogenin, VEGF, fibroblast growth factor (FGF), interleukin-6, interleukin-8 and tissue inhibitors of metalloproteinases 1 and 2 (TIMP-1 and TIMP-2)." (PMID 32823989, 2020). "Moreover, altered extracellular matrix proteins in glioblastoma induce the up-regulation of Matrix metalloproteinase-9 (MMP9) and Metalloproteinase inhibitor 1 (TIMP1) proteins that disrupt normal angiogenesis and promote tumor invasion." (PMID 31357616, 2019). "In addition, α-H also increased TIMP-1 expression and inhibited mRNA expression and protein levels of MMP-2 and MMP-9 and hence their enzymatic activities, which may be associated to the reduced migration and invasion capacities of glioblastoma cells exerted by α-H." (PMID 31551765, 2019). "Co-expression of TIMP-1 and stem cell markers as well as the wide expression of CD63 might suggest a role for TIMP-1 and CD63 in glioblastoma stemness." (PMID 29523123, 2018). "A high plasma level was not necessarily associated with a high TIMP-1 immunoreactivity in the biopsy and high TIMP-1 immunoreactivity was detected in many glioblastoma biopsies with normal plasma TIMP-1." (PMID 27619981, 2016).
glioblastoma (continued). "In total mRNA expression of TIMP-1, ANGPT1, SPP1, TGF-β1 and YKL-40 genes was analysed in 61 patients with different grade astrocytoma: 20 grade II diffuse astrocytoma, and 41 grade IV astrocytoma (glioblastoma), and in case of IP-10—in 11 grade II diffuse astrocytoma, and 24 glioblastoma samples." (PMID 34162919, 2021). "Whether TIMP-1 and CD63 can interact on the surface of glioblastoma cells is so far unknown." (PMID 29523123, 2018). "A significant correlation was found between TIMP-1 and CD63, and the TIMP-1 and CD63 proteins were co-expressed at the cellular level and located in close molecular proximity, suggesting that TIMP-1 and CD63 could be co-players in glioblastomas." (PMID 29523123, 2018). "The blood brain barrier may play a role in the lack of increased TIMP-1 protein in blood samples from glioblastoma patients." (PMID 27619981, 2016). "In general, the TIMP-1/CEN-X ratio was close to 1, but varied between 0.7 and 1.09, however, we did not have pre-defined cut-off values for TIMP-1 amplification or deletion, since, to our knowledge, TIMP-1 FISH analysis in glioblastomas or other cancers has not been described before." (PMID 27619981, 2016). "Another upregulation compared to the control was detected only in the glioblastoma group for the MMP9 (2.43) and TIMP1 (10.3) genes, both without significance, as well as in meningiomas (TIMP1 = 22.4)." (PMID 38474106, 2024).
hepatocellular carcinoma (36 papers, 2011 to 2025). A malignant tumor that arises from hepatocytes. "High expression of TIMP-1 has been reported in hepatocellular carcinoma tissues associated with advanced TNM stage, intrahepatic metastasis, portal vein and vascular invasion." (PMID 29393911, 2018). "A recent study showed that in hepatocellular carcinoma cells TIMP1 expression is associated with advanced TNM stage (classification of malignant tumors), intrahepatic metastasis, portal vein invasion, and vasculature invasion." (PMID 28430130, 2017). "TIMP-1 overexpression is associated with hepatocellular carcinoma (HCC) lung metastases, while TIMP-2 expression is downregulated in patients with HCC." (PMID 38067256, 2023). "The removal of TIMP-1 by immunoprecipitation abolishes hepatocellular carcinoma cell proliferation and migration, showing that TIMP-1 relays pro-metastatic signals of TGF-β between different cells." (PMID 38351317, 2024). "CD63 is the only known membrane receptor that directly interacts with TIMP1 in numerous malignancies, including hepatocellular carcinoma and other inflammatory diseases." (PMID 35140332, 2022). "We then show that TIMP-1 and caveolin-1 expression increasesin cirrhosis and hepatocellular carcinoma." (PMID 35255206, 2022). "TGFβ-induces TIMP1 from hepatic stellate cells, subsequently bound to CD63, leading to FAK activation in hepatocellular carcinoma cells, suggesting that TIMP1 can function as a mediator of TGFβ-regulated crosstalk between stromal and cancer compartments." (PMID 34638439, 2021). "TIMP-1 overexpression was shown to facilitate the EMT of hepatocellular carcinoma (HCC) cells via MMP-independent activities such as modulating apoptosis, mitogenic activity, and cellular proliferation and morphology." (PMID 32466129, 2020). "Elevated TIMP-1 expression is described as a poor prognostic plasma biomarker in several cancers including, renal cell, pancreatic, and hepatocellular carcinoma." (PMID 29137288, 2017). "Moreover, TIMP-1 displays anti-apoptotic properties, in patients with hepatocellular carcinoma (HCC) TIMP-1 serum levels are elevated and high TIMP-1 expression levels in HCC are associated with a poor prognosis." (PMID 28386095, 2017). "This is similar to previous reports that TIMP-1 reduced the growth rate of the hepatocellular carcinoma cells (BEL-7402) by upregulation of p21." (PMID 27239203, 2016). "STAT3 has been shown to directly target the TIMP-1 gene as IL-6 has been observed to up regulate TIMP-1 levels in a STAT3-dependent manner in human hepatocellular carcinoma cells as well as human fibroblasts." (PMID 24743777, 2014). "This exhibits that up-regulation of TIMP-1 is responsible for the anti-metastatic potential of genipin in hepatocellular carcinoma." (PMID 23029478, 2012). "According to the expression levels of GRP78, MMP-2, MMP-9, MMP-14 and TIMP-1 in hepatocellular carcinoma cell lines SMMC7721 and hepG2, we used SMMC7721 as the in vitro invasion model for further functional analysis." (PMID 22546345, 2012). "TIMP-1 was reported to inhibit both MMP-2/9 activities in line, therefore the inhibition of MMP-2 activities in human hepatocellular carcinoma cells exposed to genipin may be attributable to up-regulation of TIMP-1." (PMID 23029478, 2012). "Our findings demonstrated the potential of genipin in suppressing hepatocellular carcinoma metastasis, and p38/TIMP-1/MMP-2 pathway may be involved as the key mechanism of its anti-metastasis effect." (PMID 23029478, 2012). "Our results demonstrate that genipin presents similar anti-metastatic effect by activating p38 MAPK to induce TIMP-1 expression in hepatocellular carcinoma, indicating that genipin may be on the list of potential therapeutic agents against human cancer." (PMID 23029478, 2012). "An IL-6 dependent TIMP-1 induction was recently demonstrated in a hepatoma cell line." (PMID 21573245, 2011).
hepatocellular carcinoma (continued). "In conclusion, the present study highlighted the critical roles of MET, TIMP1, and VTN in the progression of MVI in hepatocellular carcinoma, underscoring their previously unreported contributions to this process." (PMID 39944086, 2025). "Upregulation of TIMP-1 and TIMP-2 led to inhibition of cell migration and invasion in hepatocellular carcinoma cells." (PMID 31726667, 2019). "In hepatocellular carcinoma, high levels of MMP-8 and TIMP-1 have indicated poor survival, as did our levels in CRC." (PMID 29929486, 2018). "Thus, TIMP-1-deficient mice are not protected from the development of hepatocellular carcinoma." (PMID 28386095, 2017). "It has also been demonstrated that CnP inhibits TGF-β-induced apoptosis in rat hepatoma cells, and, consistently, we showed that CnP significantly decreased hepatic TGF-β mRNA levels, along with those of MCP-1 and TIMP-1." (PMID 28594915, 2017). "Study has shown that TIMP-1/-2 and MMP-9 all play crucial roles in the tumor cell growth and invasion of hepatocellular carcinomas." (PMID 28767067, 2017). "Hepatoma cell lines co-cultured with primary HSCs induced fibrotic activation by secreting fibrogenic factors, increasing the production of collagen type I alpha 1 (COL1A1) and TIMP metallopeptidase inhibitor 1 (TIMP1)." (PMID 41149169, 2025). "Meanwhile, the expression of TIMP1 and CAV1 increases in cirrhosis and hepatocellular carcinoma." (PMID 36146640, 2022). "We found in CRC that although MMP-9 levels had no influence on survival, patients with a low MMP-9/TIMP-1 ratio had impaired survival, in line with their results in hepatocellular carcinoma." (PMID 29929486, 2018). "In hepatocellular carcinoma (HCC), CAFs adjacent to tumors express MMP‐9 and TIMP‐1 in a spatially restricted manner, promoting ECM degradation at the invasion front while preserving structural integrity elsewhere." (PMID 40656546, 2025). "Although TIMP1 functions as a matrix metalloproteinase inhibitor capable of restraining MMP-mediated matrix degradation, contemporary studies confirm its capacity to activate PI3K/Akt signaling through CD63 binding, promoting hepatocellular carcinoma stem cell self-renewal." (PMID 41450464, 2025).